MATN4 (matrilin 4)
Description:
Major component of the extracellular matrix of cartilage.
Tractability: Antibody: its Gene Ontology location is reachable by antibodies, with high confidence; UniProt places it where antibodies can reach, with medium confidence; UniProt predicts a signal peptide or a membrane-spanning region.
Gene: Protein-coding gene on chromosome 20 (45,293,445 to 45,312,469, reverse strand). Ensembl gene ENSG00000124159.
Subcellular location: Secreted
Pathways (Reactome):
Extracellular matrix organization: ECM proteoglycans
Gene Ontology:
Molecular function: protein binding; calcium ion binding
Biological process: extracellular matrix organization
Cellular component: matrilin complex; extracellular matrix; extracellular region; non-collagenous component of interstitial matrix
Genetic constraint (gnomAD): Loss-of-function variants: 40 observed, 48.26 expected, observed/expected ratio (o/e) 0.83, 90% interval 0.64 to 1.08. The upper end of that interval is the gene's LOEUF score, 1.08, which puts it in group 4 of 6, group 1 being the genes least tolerant of losing a copy. Missense variants: 810 observed, 784.49 expected, observed/expected ratio (o/e) 1.03, 90% interval 0.97 to 1.09. Synonymous variants: 351 observed, 333.42 expected, observed/expected ratio (o/e) 1.05, 90% interval 0.96 to 1.15.
Homologues: Orthologues: chimpanzee MATN4 (99% identical), macaque MATN4 (95% identical), pig MATN4 (93% identical), guinea pig MATN4 (91% identical), rat Matn4 (90% identical), mouse Matn4 (90% identical), dog MATN4 (88% identical), tropical clawed frog matn4 (64% identical), zebrafish matn4 (63% identical), rabbit MATN4 (55% identical). Paralogues in human: MATN2 (49% identical), MATN1 (43% identical), MATN3 (30% identical), COL14A1 (27% identical), COL12A1 (26% identical), COL6A6 (26% identical), COL6A3 (24% identical), VWA2 (23% identical), COL6A5 (22% identical), COCH (21% identical), VIT (12% identical), VWA1 (11% identical).
Diseases named in the same sentence as MATN4 in open-access papers:
MATN4 is named in the same sentence as 13 diseases in open-access papers, as found by Europe PMC text mining. Sharing a sentence is not in itself a finding about the gene and the disease. The quoted sentences say what the papers report.
osteoarthritis (2 papers, 2020 to 2023). A noninflammatory degenerative joint disease occurring chiefly in older persons, characterized by degeneration of the articular cartilage, hypertrophy of bone at the margins and changes in the synovial membrane. "Matn1-4−/− and Matn4−/− mice develop similar age-associated osteoarthritis suggesting a novel function of matrilin-4 for preventing articular cartilage degradation in the murine knee joint." (PMID 31963938, 2020). "Interestingly, similar articular cartilage degeneration was observed in aged matrilin-4 deficient mice, indicating an unexpected role of matrilin-4 in protecting articular cartilage from age-associated, spontaneous osteoarthritis." (PMID 31963938, 2020). "Interestingly, Matn4−/− mice also developed age-associated osteoarthritis suggesting a crucial role of MATN4 in maintaining the stability of the articular cartilage." (PMID 31963938, 2020). "We found evidence for biochemical compensation within the matrilin family, which showed that matrilins are important for patterning of the vertebral column and they, especially MATN-4, protect articular cartilage against spontaneous, age-associated osteoarthritis." (PMID 31963938, 2020). "Matn4−/− mice spontaneously developed osteoarthritis, accompanied by changes in the biomechanical properties of articular cartilage." (PMID 37259472, 2023). "Matn4−/− animals, similar to the Matn1-4−/− mice, exhibited severe osteoarthritis-like phenotype at the age of 24 months often leading to complete erosion of the articular cartilage and exposure of the subchondral bone." (PMID 31963938, 2020). "We found that the mean articular cartilage degeneration score was 1.70 in wild-type mice and was 3.67 in the Matn4−/− mice (p < 0.001), implying that MATN4 may protect against osteoarthritis." (PMID 31963938, 2020).
breast carcinoma (1 paper, 2022). "The role of MATN4, SLC6A17, and NEUROG2 genes in breast cancer is currently unknown, but they play a role in other cancers, which may be an inspiration for future breast cancer gene research." (PMID 36553681, 2022).
chondroblastic osteosarcoma (1 paper, 2011). An osteosarcoma characterized by the presence of atypical cartilage of variable cellularity. "The genes that make up the chondroblastic-specific part of this expression profile are mostly chondroid matrix-associated genes, such as ACAN, COL2A1, and MATN4, and are all upregulated in chondroblastic osteosarcoma." (PMID 21933437, 2011).
corneal stromal dystrophy (1 paper, 2012). "The present study investigated the expression patterns of fibrillin-2, tenascin-C, matrilin-2, and matrilin-4 in granular and lattice type I corneal stromal dystrophy samples." (PMID 22876117, 2012). "Immunolocalization of fibrillin-2, matrilin-2, matrilin-4, and tenascin-C in normal and stromal dystrophy corneas (maximum and minimum gray levels are 0 and 255, respectively)." (PMID 22876117, 2012).
diabetic neuropathy (1 paper, 2023). A chronic, pathological complication associated with diabetes mellitus, where nerve damages are incurred due to diabetic microvascular injury involving small blood vessels that supply these nerves, resulting in peripheral and/or autonomic nerve dysfunction. "For diabetic neuropathy, gene GFY (rs4802605), ADH4 (rs4148883), LRFN2 (rs61731010), PKHD1 (rs2499486), SLC11A1 (rs17235409), MATN4 (rs2072788), and PPARA (rs4253772) were associated or contributed to the biological relevance to the pathogenesis of the complication." (PMID 37033211, 2023).
fibrosis (1 paper, 2025). the formation of excess fibrous connective tissue in an organ or tissue in a reparative or reactive process. "However, genes associated with cartilage fibrosis (such as Sparc and Col1a1) and hypertrophy (e.g., Ibsp, Bmp2, Mmp13, and Matn4) presented the highest expression levels at 6 weeks." (PMID 40722047, 2025).
lattice type I corneal dystrophy (1 paper, 2012). "Fibrillin-2, tenascin-C, matrilin-2, and matrilin-4 may be markers of the pathogenesis of either granular or lattice type I corneal dystrophy, as revealed by immunohistochemical analysis." (PMID 22876117, 2012). "Fibrillin-2, tenascin-C, matrilin-2, and matrilin-4 may be characteristic of the pathogenesis of either the granular or lattice type I corneal dystrophy, as revealed by immunohistochemical analysis." (PMID 22876117, 2012).
osteosarcoma (1 paper, 2024). A usually aggressive malignant bone-forming mesenchymal neoplasm, predominantly affecting adolescents and young adults. "This evidence indicates that knockdown of HIF-1α reduces the promoting effects induced by MATN4 overexpression on the proliferation, migration and invasion of osteosarcoma cells under hypoxia." (PMID 38889378, 2024). "Knockdown of MATN4 inhibits the proliferation, migration, and invasion abilities of osteosarcoma cells and reverses the promoting effects of hypoxia on these functions." (PMID 38889378, 2024). "Subsequently, we proceeded to authenticate its expression in both osteosarcoma cells and tissues, thereby implying a potential correlation between the expression magnitude of MATN4 and the metastatic potential of osteosarcoma." (PMID 38889378, 2024). "Interestingly, knockdown of HIF-1α reduces the stimulatory effects of MATN4 overexpression on the proliferation, migration, and invasion of osteosarcoma cells under hypoxic conditions." (PMID 38889378, 2024). "Notably, MATN4 exhibited a substantial increase in osteosarcoma cells with a pronounced ability to metastasize, indicating its potential contribution to the proliferation and metastasis of osteosarcoma." (PMID 38889378, 2024). "However, the effect of MATN4 on tumors, especially osteosarcoma, has rarely been studied." (PMID 38889378, 2024). "In order to assess the potential correlation between hypoxic conditions and the expression of MATN4 mRNA and protein, we conducted an investigation into the impact of varying durations of hypoxia on MATN4 expression in 143b and HOS osteosarcoma cell lines." (PMID 38889378, 2024).
tumor (2 papers, 2006 to 2015). "This is substantiated by the fact that KLK14, via its serine protease activity, is able to degrade components of the extracellular matrix, including collagen IV α1 chain, collagen XII and matrilin-4 in vitro, which may promote tumour cell invasion and metastasis in vivo." (PMID 16434994, 2006). "Examples of tumor-related overexpressed genes which become promoter hypomethylated during carcinogenesis includes, but not limited to, Sonic Hedgehog, P-cadherin, and CDH3, as well as MATN4 and CTSL2, supporting the data reported here for BST-2." (PMID 25860442, 2015).
peripheral neuropathy (1 paper, 2024). A disorder affecting the peripheral nervous system. "Through MR analysis, we identified eight proteins (UBC12, SEM4C, IL_23_R, prothrombin, CBS, Microglobulin, MATN4, and COLEC12) with causal relationships to peripheral neuropathy." (PMID 39268072, 2024).
MATN4 also shares sentences with these, for which no sentence is quoted: cancer (1 paper); corneal dystrophies (1); Obesity (1).